FOXP3 (forkhead box P3)
Diseases named in the same sentence as FOXP3 in open-access papers (continued):
Sharing a sentence is not in itself a finding about the gene and the disease.
infection (continued). "The Th2 CD4+ T cells expressing IL-4 and Treg cells expressing CD4+CD25+Foxp3+ and CD4+CD25–Foxp3+ were significantly induced at the early intestinal stage (6 days post-infection, day 6) and NBL migration stage (day 15) compared to the those of uninfected mice." (PMID 31703440, 2019). "We next evaluated whether the relationship of Foxp3+ Tregs and SIV-specific CD8+ T cells changed from early stages of infection to chronic infection." (PMID 30897187, 2019). "We next investigated whether Foxp3+ cells were in contact with and potentially inhibiting the function of follicular SIV-specific CD8+ T cells in early infection." (PMID 30897187, 2019). "Interestingly, at early infection a significant proportion of IFN-γ and TNF-α producing cells predominantly from CD4+CD25− and CD4+FoxP3− T cell were observed." (PMID 31031744, 2019). "This delayed increase of Foxp3/decrease of IFN-γ and increase of serum IL-10 level at the late infection stage match previous observations at the late stage of infection of human AE (24, –, 26) and are in agreement with the data usually reported from lymphocyte studies in secondarily infected mice." (PMID 30037796, 2018). "The mRNA levels of ileal Tnfα, Il-1β, Il-22, Il-10, Foxp3 and RegIIIγ were comparable between Tac and Jax mice regardless of infection status." (PMID 29789574, 2018). "Our data additionally demonstrate that IL-21 is not highly expressed in Foxp3+TFR cells during LCMV Cl13 infection, further indicating that IL-10+IL-21+Tfh cells are distinct from the TFR lineage." (PMID 30487586, 2018). "During the course of infection, Foxp3 expression did not change significantly at 1 and 3 dpi in any of the groups analyzed." (PMID 29970179, 2018). "Sorted spleen Foxp3-GFP+ cells (5 × 105) from non-infected mice were transferred intratracheally into WT or CCR4−/− mice at 60 days of infection." (PMID 30584243, 2018). "No increase in CD19, IL17, or FoxP3 was evident at any time during the course of the infection, suggesting that there is no significant infiltration by B cells, TH17, or Treg cells into the eye during infection." (PMID 29802245, 2018). "In our current study utilising an acute infection model we did not observe an increase in Foxp3+ cells in the jejunum." (PMID 29028844, 2017). "Furthermore, DPG-3 PDDC led to a significant increase of Foxp3 on CD4+ T cells, which was significantly reduced when HIV gp120 treatments blocked DC-SIGN before infection or when cultures were stimulated with LAC." (PMID 28198424, 2017). "No change in percentage or absolute number was observed in Foxp3+ CD4+ T cells from one to six days after infection." (PMID 28474504, 2017). "To document increased Foxp3 expression in Treg cells for these studies, we harvested peripheral blood Treg cells from FIV− control cats and FIV+ cats 1 week, 4 weeks, 8 weeks and 24 weeks post infection (p.i.)and from the lymph node at 24 weeks p.i.." (PMID 29056671, 2017). "Furthermore, a marked reduction in pulmonary Treg (CD4+ CD25+ Foxp3+) cells was observed in IDO1−/− mice at weeks 2 and 10 of infection." (PMID 28791025, 2017). "The discovery of the bona fide transcription factor Foxp3 advanced the field since it is distinctive of Treg and separates them from non-Treg during ongoing infections." (PMID 28421070, 2017). "Foxp3 expression in peripheral blood Treg cells is dynamic during the acute phase of FIV infection and was higher in the peripheral blood of FIV+ cats at 6 weeks post infection, compared to FIV− cats." (PMID 29056671, 2017). "Consistent with what was found in spleen tissue at 28 days post-infection, the transcription factor Foxp3, showed no increase in mRNA or protein in splenic CD4+ T cells at this time point." (PMID 28103263, 2017).
infection (continued). "To evaluate whether S. Typhimurium infection induces the differentiation of Treg cells in these tissues, C57BL6 mice we orally infected with 1 × 105 CFUs and 96 h post-infection were measured the amount of CD4+CD25+FoxP3+ and CD4+CD25+FoxP3− T cells in situ." (PMID 28824622, 2017). "Percentages of Foxp-3+ HA-specific CD4+ T cells in the lungs were comparable among the mice with no treatment, with Oseltamivir only and with combinations of Oseltamivir and Rapamycin on day 7- post infection." (PMID 28646236, 2017). "FoxP3+ and IL‐10+ frequency within CD4+ T cells was significantly higher in peritoneal exudate cell PECs and spleen cells of E. multilocularis infected (AE‐WT) mice at 4 months post‐infection (p.i.)when compared to non‐infected WT‐controls." (PMID 28621034, 2017). "Ccr5−/− recipients of CCR5+CD4+Foxp3+ Tregs had a higher number of CD4+Foxp3+ Tregs in the CNS at 5 days after infection, compared to Ccr5−/− mice that did not receive Tregs." (PMID 27439902, 2016). "The second part of the review will focus on how HIV direct infection of Tregs might jeopardize each of the mechanisms described in the first part by suppressing the Treg cornerstone molecules: CD25 and Foxp3." (PMID 27242797, 2016). "Postnatal infection lead to increased CD4+FoxP3+T-cells frequencies in adult descendants, mostly in SIM mice - Inunstimulated cultures, the infected groups showed a higher frequency ofCD4+FoxP3+ T-cells compared with the uninfected control group." (PMID 26872339, 2016). "This immune evasion mechanism might be relevant to the establishment of a chronic phase of infection and relies on the induction of regulatory CD4+ Foxp3+ T cells that actively suppress CD8+ T cell priming and curtail their functionality." (PMID 27332899, 2016). "The number of FOXP3 expressing lung CD3+CD4+ T cells was increased at 7 days post-infection in both w/t and Tbet-/- mice, but was not different between the 2 mouse strains." (PMID 27683080, 2016). "First, to evaluate whether thymic content of tTregs (detected as Foxp3+ cells inside CD4+ single-positive -CD4 SP- compartment) were affected, we monitored by cytofluorometry their frequency and cell number during infection in C57BL/6 mice." (PMID 26745276, 2016). "This developmental link between CD4+Foxp3+ Tregs and IL-17+CD4+ Th17 cells has led to speculation that these T cell subsets exist in equilibrium during inflammation and infection." (PMID 27439902, 2016). "In that work, mice given IL-12 showed a significant augment in IFN-γ production at the beginning of infection and reduction of Th1/Th2-related cytokines at the late stage of infection, similarly to what was observed in the present study for Rag1-/- mice injected with CD4+Foxp3- T cells." (PMID 26512987, 2015). "Taken together, these data demonstrate that infections and inflammatory conditions can induce IL-17A production in a fraction of Foxp3+Tregsin vivo, but do not affect their immunomodulatory functions." (PMID 25790134, 2015). "During the first 3 weeks of infection, there was no expansion in the proportions or numbers of Foxp3+ Treg cells in the lymph nodes (LN) draining the skin inoculation site, the lungs, the lung-draining LN, or the spleen." (PMID 26195548, 2015). "Cytokine production analysis by flow cytometry revealed, at week 2 post-infection, higher amounts of IFN-γ in lungs of mice receiving CD4+Foxp3- T cells in comparison to the other groups, which is consistent with the elevated levels of Tbet expression found in the lungs of mice from this group." (PMID 26512987, 2015). "There was no increase in the percentage of CD4+ Foxp3+ Treg cells expressing IL-10 upon infection in either the tLN or spleen." (PMID 26195548, 2015). "Intracellular staining of CD4+ T lymphocytes revealed that mice reconstituted with CD4+Foxp3- T cells and CD4+Foxp3- T cells + Treg showed augmented production of IFN-γ, IL-17 and IL-4, at weeks 2 and 6 post-infection, when compared with mice receiving Treg cells only." (PMID 26512987, 2015).
infection (continued). "Foxp3+ Treg cells rapidly become activated and increase in number during the larval stages of Litomosoides sigmodontis infection, and ablation of CD25+ Treg cells before or during infection enhances parasite killing." (PMID 26195548, 2015). "Infection also failed to stimulate the production of IL-10 by Foxp3+ Treg cells, despite increased IL-10 production by CD4+ Foxp3− IL-4+ Th2 cells." (PMID 26195548, 2015). "Notably, the expression intensity of Foxp3 was significantly lower in naïve IL-6−/− compared with that in BALB/c mice, while the disparity between the strains narrowed following infection." (PMID 24185641, 2014). "By contrast a lack of IFN-γ, induction of FoxP3+ T cells and increased IL-1β and IL-10 secretion were indicative of progressive infection in Sham vaccinated animals." (PMID 25480162, 2014). "To assess the effect of Ad5hr infection on CD4+ regulatory T cells, we evaluated the frequency of CD4+ Treg (Foxp3+/CD25hi) and a CD4+ Treg subset expressing CTLA4 (Foxp3+/CTLA4+/CD25hi) that is thought to be particularly immunosuppressive, as CTLA4 is required for suppression by Tregs." (PMID 25203111, 2014). "Furthermore, our study also showed decreased expression of the chemokines CCL3, CCL4 and CCL5 in the liver and ileum of CCR5-/- mice along with reduced induction of the transcription factors Foxp3, T-bet and GATA-3 after infection." (PMID 25119429, 2014). "Our studies appear to indicate that at an early phase of infection NO does not affect the expansion of CD4+CD25+Foxp3+ regulatory T cells." (PMID 23936574, 2013). "Additionally, there was some Foxp3 expression by CD8+ cells, which increased significantly at day 42 post infection in B6.CCR7-/- mice." (PMID 24205367, 2013). "However, following infection the IL-10 came from both CD4+Foxp3− and CD4+ Foxp3+ T cells, and about 50% of the CD4+Foxp3− T cells producing IL-10 also produced IFN-γ." (PMID 23555256, 2013). "In several animal infection models, helminth parasites such as H. polygyrus, Litomosomoides sigmodontis or Schistosoma mansoni, induce regulatory responses via different regulatory cells, most prominently the CD4+CD25+Foxp3+ population." (PMID 23844022, 2013). "In agreement with a lack of role for Foxp3+ Tregs in the development of chronic T. muris infection, we did not see any enhancement of Foxp3+ Treg levels during the course of infection." (PMID 24098124, 2013). "Thus, CD4+Foxp3+ Treg cells appear to be the predominant T-cell source of IL-10 at the infection site, whereas in the LN IL-10 also emanates from CD4+Foxp3− Teff cells." (PMID 23319295, 2013). "However, following infection, the TLR2KO mice displayed decreased frequencies of Foxp3+ Tregs in the lungs compared to WT." (PMID 23785280, 2013). "We therefore studied LCMV-DOC infection using the DEREG mouse model, in which Treg cells can be ablated by diphtheria toxin (DT) treatment due to transgenic expression of a high affinity DT receptor under control of the Foxp3 promoter." (PMID 23696736, 2013). "Upon H. polygyrus infection the numbers of Foxp3+ Treg cells in the MLN of WT mice significantly increased 73% by day 7 post-infection (pi), however, there was no early expansion of Foxp3+ Treg cells at this time point in ICOS−/− mice." (PMID 23319295, 2013). "Alongside the expected upregulation of ICOS by CD4+Foxp3− Teff cells during both infections, CD4+Foxp3+ Treg cells showed increased expression of ICOS over the first 4 weeks of H. polygyrus infection and during the acute egg phase (weeks 6–8) of S. mansoni infection." (PMID 23319295, 2013). "Only a small statistically not significant number of Foxp3+ T cells was detected in the brain, irrespective of the infection (data not shown)." (PMID 22448284, 2012). "In contrast to the expansion of IL-10-producing CD4+ T cells, the frequency of splenic Foxp3+ Treg did not increase during infection, but instead decreased as previously reported." (PMID 22911108, 2012).
infection (continued). "The partial depletion of CD4+CD25+Foxp3+ cells by anti-CD25 treatment could, at least in part, explain the low numbers of CD4+CD25+ cells detected in the lungs of the A/J mice at week 2 of infection." (PMID 23226464, 2012). "We nevertheless confirmed that infection of DCs with SIVmac VLP alone did not compromise their ability to induce FOXP3." (PMID 22912740, 2012). "Although T-bet and CD127 expression were not directly addressed, Foxp3− ‘effector’ CD4+ T cells also appear to be the major CD4+ T cell subset producing IL-10 during infection of mice with L. major." (PMID 22911108, 2012). "By contrast, there was no significant increase in Foxp3+Heliosnegative cells in the lungs of either BALB/c or CBA/Ca mice over the course of the infection (data not shown)." (PMID 22563306, 2012). "Upon infection, FOXP3+ non-Tregs markedly down-regulates its capacity to produce Th1 and Th17 cytokines, however, they retain the ability to produce substantial amounts of Th2 cytokines." (PMID 23285102, 2012). "Foxp3+Helios+ cells increased approximately 3-fold over the first 24 hours p.i. in BALB/c mice, but not in CBA/Ca mice (p<0.001), indicating that BALB/c T regulatory cells are activated rapidly following infection." (PMID 22563306, 2012). "However, compared with B10.A mice, and at both post-infection periods, higher numbers of CD4+CD25+Foxp3+ Treg cells were found in A/J mice." (PMID 23226464, 2012). "When treated with APS (200 μg/ml) for 24 h ex vivo, the intranuclear Foxp3 protein, Foxp3 mRNA expressions and IL-10 secretion of CD4+CD25+Tregs isolated from burn plus infection mice on PBD 3 and 7 were obviously lower than those in untreated burn plus infection mice on PBD 3 and 7 (P<0.05)." (PMID 21698274, 2011). "The primary difference between the two virus infections is that H310A1 infection activates CD4+CD25+FoxP3+ Treg cells which are absent in H3 infected mice." (PMID 21255407, 2011). "More than 75% of CD4+CD25+ mLN cells co-expressed FoxP3, regardless of the stage of infection confirming that the majority of CD4+CD25+ cells can be classified as CD4+FoxP3+Tregs." (PMID 21858239, 2011). "Western Blots analysis of Foxp3 protein expression indicated that Foxp3 proteins (48 kD) in infected CXCL-10-/- peaked at day 4 at higher level than in uninfected controls at day 2 and 8 post-infection." (PMID 21439091, 2011). "Since we observed heightened bioactive TGFβ1 from mLN cells and within the colon at the chronic phase of infection, we speculate that TGFβ1 might have a role in the induction of gut-homing CD4+FoxP3+Tregs from naïve precursors." (PMID 21858239, 2011). "FoxP3, a marker of Treg activity, increases in CD4+CD25+ T cells following FIV infection." (PMID 20507636, 2010). "Interestingly despite dramatic shifts in the percent and absolute number of CD4+ T cells among splenocytes, the percent Foxp3+ Tregs among CD4+ T cells remains remarkably stable and essentially unchanged at approximately 10% throughout the infection." (PMID 20714351, 2010). "By extension, at later time points after infection (day 37) when CTLA-4 expression is down-regulated on Foxp3+ Tregs, no significant change in Salmonella bacterial burden or T cell activation occurred with CTLA-4 blockade." (PMID 20714351, 2010). "In confirmation of this, by day 7 post-infection, IL-10+ CD4+ T cells were almost exclusively CD25− indicating that, since the majority of Foxp3+ cells maintain CD25 expression during P. yoelii infection, CD25−Foxp3− CD4+ T cells are the primary source of IL-10 during both PyL and PyNL infection." (PMID 18401464, 2008). "FoxP3-expressing cells stimulated at suboptimal levels of anti-CD3 antibody also displayed a very similar enhancement of infection compared to HDV-transduced cells (data not shown)." (PMID 15252446, 2004).
infection (continued). "This segregation was largely driven by increased frequencies of plasmacytoid dendritic cells (pDC, cluster 43), CD45RA+Foxp3+CD4+T cells (resting Tregs, cluster 7), and basophils (cluster 35) as well as decreased frequencies of memory CD4+T cells (clusters 4, 9, and 19) after infection." (PMID 39013877, 2024). "We investigated whether the absence of IL-4Rα on Foxp3 Treg cells influenced the lung cytokine profile in tissue homogenates at 3 and 18 weeks post-infection (wpi)." (PMID 39483462, 2024). "CD8, γδ-T cells (positive for γδ-TCR and γδ-WC1), NKp46, TNF-α, FoxP3, and IL-10 cell labelling were significantly lower in NC than in DL, and the estimated differences between the NC group and the three infection groups were generally similar, though not consistently statistically significant." (PMID 37375536, 2023). "At week 4 post infection, CD4+ T-cells showed a mixed response to S. mansoni AWA by secreting cytokines which encompassed Th1 (IFNγ, TNFα, IL-2 & IL-1β), Th2 (IL-4, IL-5, IL-13) and regulatory responses (IL-10) as well as the regulatory T cell transcription factor Foxp3." (PMID 37837930, 2023). "Therefore, Foxp3+ Treg differentiation may also be mediated by molecules other than LAG3, particularly during the middle stage of infection." (PMID 37172058, 2023). "Surprisingly, the frequency of AhR-dependent Rorγt+FoxP3− Th17 cells, essential for protection against C. rodentium, was increased in the siLPL and mLN of TDD-fed mice; however, IL-17 production from these cells in the colon, the site of infection, was reduced." (PMID 36840944, 2023). "In addition, FoxP3+ CD25+ in CD4+ T cells increased with infection, both in frequency and number, in relation to non-infected mice." (PMID 36271272, 2022). "However, frequencies of CD4+ICOS+Foxp3+ Treg cells during infection with non-lethal parasite remains significantly low (approximately 4%) by day 10th post infection." (PMID 35109868, 2022). "Furthermore, the increase in LAP(TGF-β1)+ FoxP3+ CD8 T-cells during untreated infection is supported by a report of a positive correlation between TGF-β1 production and FoxP3+ CD8 T-cells frequencies in non-pathogenic SIV infection in African green monkeys." (PMID 35967314, 2022). "Furthermore, the decreased percentage of CD4+FoxP3+ T cells in the total lung lymphocyte population of IFT88 KO mice is not dependent on infection with Mabs and is apparent 3 months after deletion of the IFT88 gene (treatment with tamoxifen)." (PMID 36505420, 2022). "Our data in this study showed more severe infection and diseases in SND1-/- mice, which correlated with significantly reduced Th1/17 immune responses, including lower levels of Cm-driven IFN-γ and local IL-12 production, higher levels of CD4+Foxp3+ Treg cells, and impaired function of DC." (PMID 33635920, 2021). "Regulatory T-cells (TREG, CD4+CD44+FoxP3+) ranged from 20% - 25% of activated CD4+ T-cells during UgCl223 infection and, unlike in lethal KN99α infections, were present at significantly lower levels compared to the predominant TH1 effector cell populations at all but the 0- and 77- day timepoints." (PMID 35186781, 2021). "At 14 dpi, numbers of Foxp3+ regulatory T cells (p = 0.018) and Foxp3 mRNA copy numbers (p = 0.009), determined by immunohistochemistry and RT-qPCR, respectively, were significantly increased in brain samples of mice with intact DCIR signalling (WT mice) compared to DCIR−/− mice upon infection." (PMID 34893671, 2021). "Similarly, schistosome eggs show the ability to induce a significant Foxp3+ Treg cell response, which suggests that SEA may be the most potent inducer for the generation of nTregs during infection." (PMID 32132991, 2020). "The increased expression levels of IDO1, TGF-β1 and FoxP3, in women who cleared their infection, may suggest that during the combined effect of highly expressed levels of IDO1 and TGF-β1, this induces the expression levels of FoxP3, an indicator of regulatory immune response." (PMID 30832593, 2019).